CAT (catalase)
Diseases named in the same sentence as CAT in open-access papers (continued):
Sharing a sentence is not in itself a finding about the gene and the disease.
pulmonary fibrosis (34 papers, 2010 to 2025). Chronic progressive interstitial lung disorder characterized by the replacement of the lung tissue by connective tissue, leading to progressive dyspnea, respiratory failure, or right heart failure. "We thus postulated epithelial damage would be associated with a functional deficiency of catalase during the development of lung fibrosis." (PMID 21190578, 2010). "Notably, MCAT mice that globally overexpress mitochondria-targeted human catalase have reduced asbestos- and bleomycin-induced lung fibrosis that occurs in association with reduced levels of AEC mitochondrial ROS production and AEC and lung mtDNA damage." (PMID 34202229, 2021). "Decreased lipid peroxidation at T2, assessed through TBARS, suggests a delay or even prevention of pulmonary fibrosis, also due to higher plasmatic values of CAT and SOD that act as ROS scavengers." (PMID 33572362, 2021). "We found increased levels of MDA and decreased activity of SOD and CAT in animals subjected to bleomycin-induced pulmonary fibrosis treated with Vehicle only in comparison to Sham, as also observed in previous investigations." (PMID 34065064, 2021). "It has been reported that intratracheal administration of catalase in asbestos-treated mice prevents the development of pulmonary fibrosis by inhibiting the generation of H2O2 in inflammatory cells." (PMID 35126133, 2021). "Evidently, the activities of SOD and catalase decreased in the H2O2-induced lung fibrosis models, and siRNA-TERRA promoted SOD and catalase activities." (PMID 29197377, 2017). "Taken together, these findings demonstrate diminished catalase expression and activity in human pulmonary fibrosis and suggest the protective role of catalase against bleomycin-induced inflammation and subsequent fibrosis." (PMID 21190578, 2010). "The regulatory mechanisms and role of catalase in the development of pulmonary fibrosis have largely remained to be determined." (PMID 21190578, 2010). "The data suggest that catalase is downregulated at transcriptional levels, resulting in impaired catalase activity in bleomycin-induced lung fibrosis in mice, as was seen in human IP lungs." (PMID 21190578, 2010). "This increased mitochondrial synthesis of ROS is important in the genesis of pulmonary fibrosis because in experimental models, it was shown that mice that overexpress mitochondria-targeted catalase (a ROS scavenger) show partial protective effects against the development of pulmonary fibrosis." (PMID 41597294, 2025). "The effect of N. sativa on oxidative stress through decrease production peroxidation and increasing catalase activity may also support its effect in treatment of diseases such as pulmonary fibrosis in which free radicals play an important role." (PMID 29881712, 2018). "In order to investigate whether catalase activity and mRNA are also decreased during the development of lung fibrosis, C57BL/6J mice were subjected to intratracheal administration of bleomycin." (PMID 21190578, 2010). "In this study, we found catalase has a protective role in the lung fibrosis." (PMID 21190578, 2010). "Our result that catalase is decreased in bleomycin-induced lung fibrosis might be due to changing cellular dynamics during progression, however, the finding that the acatalasemic mice get more fibrosis supports the functional role of catalase in preventing fibrosis." (PMID 21190578, 2010). "Finally we examined whether the lowered catalase activity in the lungs would worsen lung fibrosis induced by bleomycin." (PMID 21190578, 2010). "The importance of antioxidants in pulmonary fibrosis has been emphasized, deletion of antioxidant defenses, including CAT, GSH, SOD and Nrf2 has been revealed in animal models of pulmonary fibrosis." (PMID 38238857, 2024). "Our study found that compared to the control group, mice with pulmonary fibrosis treated with BLM had significantly higher MDA levels and lower SOD and CAT activity in lung tissue." (PMID 37781713, 2023).
pulmonary fibrosis (continued). "Hesperetin, adelmidrol, and curcumin upregulated the expression of GSH, SOD, and CAT, reduce MDA and ROS production, and suppress bleomycin- and silica-induced oxidative damage in pulmonary fibrosis." (PMID 36267093, 2022). "The antioxidant levels of CAT, GSH, MDA, NO, and SOD in the lung tissue of normal control rats and BLM-induced lung fibrosis rat model were also determined." (PMID 35268069, 2022). "SFN treatment of bleomycin-induced pulmonary fibrosis attenuates fibrosis, apoptosis and lung oxidative stress by increasing the expression of antioxidant enzymes, NQO1, HO-1, SOD and catalase, via upregulation of Nrf2 gene expression." (PMID 35126133, 2021). "Compared to WT mice, crocidolite/bleomycin-exposed mitochondrial-targeted catalase (MCAT) mice exhibit reduced pulmonary fibrosis as measured by lung collagen levels and lung fibrosis score." (PMID 34354793, 2021). "To investigate the role of the antioxidant properties of EOCW in attenuating bleomycin-induced pulmonary fibrosis, we assessed the levels of MDA produced by lipid peroxidation in situ, as well as SOD and CAT activity." (PMID 34065064, 2021). "Three studies evaluated biomarkers for lung fibrosis (vimentin,α-SMA, surfactant protein-C, MCP-1, and Krebs von den lungen-6& KC) resulting from inflammation, and three studies evaluated biomarkers relatedto oxidative stress (ROS, SOD, GSH-PX, and CAT)." (PMID 39692326, 2024). "This includes key components such as catalase, glutathione (GSH), superoxide dismutase (SOD), and nuclear factor erythroid 2-related factor 2 (Nrf2), which play a protective role in the context of pulmonary fibrosis." (PMID 37958795, 2023). "Reduced the levels of caspase-3, IL-1β, TNF-α, TGF-β, HYP, 3-NT, and 4-HNE; increased the levels of Nrf2, HO−1, NQO1, SOD1, and CAT; alleviated BLM-induced alveolar epithelial cell apoptosis, alveolitis, collagen accumulation, lung oxidative stress, and lung fibrosis." (PMID 36139759, 2022). "Previous works have reported an increase in antioxidant enzyme activities, such as SOD and catalase, during SARS-CoV2 infection, and animal studies have shown that the use of a synthetic and stable SOD has a protective effect in pulmonary fibrosis, lung inflammation, and ARDS." (PMID 36613462, 2022). "However, the distribution and pattern of catalase-positive cells are different between the groups of BLM + Nintedanib and BLM + Pirfenidone, resulting from the diverse mechanisms to treat lung fibrosis of these two medications." (PMID 33256831, 2020). "The levels of catalase activity in lung tissue were significantly lower in pulmonary fibrosis compared with controls (p = 0.0010), without any obvious difference between UIP and NSIP (318.8 ± 67.6 nmol/min/mg protein vs. 249.0 ± 29.5; NS)." (PMID 21190578, 2010).
kidney damage (33 papers, 2011 to 2025). "Deficiencies in key antioxidant enzymes, such as SOD and CAT, have been shown to exacerbate kidney damage." (PMID 41301558, 2025). "The rs1001179-A allele in the CAT gene also displayed a similar association with nephropathy (OR 0.48, 95% CI 0.26-0.87; p=0.010)." (PMID 29410390, 2018). "Previous studies have found that exposure to BPS affects the oxidative stress, cell viability, apoptosis levels and catalase (CAT) activity of mouse kidney cells, thereby causing kidney damage." (PMID 39148651, 2024). "The current study showed that the nephropathy group revealed a significant elevation in kidney function tests and lipid peroxidation markers and a significant reduction in CAT, SOD, GSH, and TAC activities following." (PMID 37631363, 2023). "Catalase depletion results in ROS accumulation in mitochondria and functional impairment, leading to kidney damage." (PMID 35269667, 2022). "An analysis of 40 single-nucleotide polymorphisms (SNPs) in 40 genes of 503 T2DM patients vs. 580 healthy controls on a Sequenom platform identified SNPs in the CAT, FTO and UCP1 genes associated with the retinopathy and nephropathy complications of T2DM." (PMID 36013384, 2022). "Cisplatin-induced kidney damage produces oxidative stress caused by large amounts of ROS and GSH depletion, decreasing the levels of antioxidant enzymes catalase, SOD, and GPx and leading to higher levels of MDA, the final product of lipid hydroperoxides." (PMID 32089779, 2020). "After stratification of patients according to the presence/absence of vascular complications, we found significant associations of variants in the CAT, FTO, and UCP1 genes with diabetic retinopathy and nephropathy." (PMID 29410390, 2018). "Qur attenuated cyclosporine-induced oxidative stress by restoring the activity of the antioxidative enzymes glutathione peroxidase and catalase, preventing its nephrotoxic action and kidney damage." (PMID 22551254, 2012). "Regarding the analysis of the results obtained related to oxidative stress, these parameters were measured since SOD and CAT are antioxidant enzymes that decrease the production of reactive oxygen species (ROS), protect against oxidative stress, nephropathy, and other T2DM complications." (PMID 38892601, 2024). "Although a decrease in CAT activity was reported in some studies in patients with nephropathy; in others, its increased activity may mean a more significant effort made by the erythrocytes to counteract the accumulation of H2O2, as a result of SOD inactivity." (PMID 36139749, 2022). "In addition, ET combined with O increased the urea concentration (but still within the normal range) and, in the kidneys, increased the IL-6 concentration and reduced catalase, in addition to preventing the increase in the degree of kidney damage." (PMID 35657982, 2022). "In contrast, another study reported that high glucose induced increased mRNA expressions of SOD1, CAT and GPx in peripheral blood mononuclear cells of type I diabetic patients without microvascular complications and decreased expression of these enzymes was found in patients with nephropathy." (PMID 36818894, 2022). "Oxidative stress-induced kidney damage can be mitigated at the cellular level through the actions of anti-oxidant enzymes, including reduced glutathione (GSH), catalase (CAT), and superoxide dismutase (SOD)." (PMID 38234666, 2024). "The activities of SOD and catalase (CAT), as well as the levels of GSH and TAC, were all dramatically reduced as a result of kidney damage induced by the HgCl2 injection in the positive control group (G2)." (PMID 39502378, 2024). "As protection against oxidant stress, the antioxidant enzymes SOD, CAT, and GSH are widely considered as powerful defense mechanisms against oxidative kidney damage." (PMID 36430889, 2022). "In contrast, after ASX pretreatment, the mice had significantly improved antioxidant enzyme activities (SOD, GSH and CAT), and improved OTA-induced kidney damage." (PMID 32197464, 2020).
kidney damage (continued). "The nephropathy and CM-treated groups had a significant (p < 0.001) increase in the mean value of lipid peroxidation markers (MDA) and a decrease in the mean value of the antioxidant marker SOD, GPx, and CAT compared with the control group." (PMID 37631363, 2023). "The striking cisplatin-induced nephropathy in the prophylactic and curative control groups was exhibited by increased levels of serum urea, serum creatinine, and tissue MDA and reduced levels of serum total protein and tissue CAT as compared to the control group at p < 0.05." (PMID 31248160, 2019).
glioma (32 papers, 2009 to 2025). A benign or malignant brain and spinal cord tumor that arises from glial cells (astrocytes, oligodendrocytes, ependymal cells). "Clinically, higher levels of CAT expression were associated with poorer overall survival rates in patients with high-grade glioma." (PMID 41009025, 2025). "Overall, these results suggest the pivotal role of CAT in promoting glioma tumorigenicity and anchorage-independent growth, a hallmark of the aggressive GBM phenotype." (PMID 34943091, 2021). "Here we also found that a shorter survival time was associated with orthotopic xenograft mice bearing glioma cell overexpression of CAT." (PMID 34943091, 2021). "Significant overexpression of CAT has been observed in a radioresistant variant clone (RRC) of U251 glioma cells." (PMID 34943091, 2021). "To evaluate the effect of CAT overexpression on glioma phenotype, we stably transfected U251 glioma cells with a vector encoding CAT cDNA." (PMID 34943091, 2021). "Together, these results confirm that human glioma tumors express high levels of CAT, and higher tumor expression of CAT is associated with poor prognosis." (PMID 34943091, 2021). "Since ROS activates signaling pathways that contribute to the regulation of cell proliferation, we investigated whether CAT overexpression in glioma cells is associated with a change in cell proliferation." (PMID 34943091, 2021). "In addition, CAT expression is inversely associated with the survival of glioma patients." (PMID 36307808, 2022). "As MnSOD and catalase are key antioxidants in glioma progression and cellular defences against oxidative stress, we evaluated their expression in U87 and U87-EGFRvIII cells." (PMID 41425707, 2025). "Typically, SOD and CAT activity is elevated in glioma and contributes to TMZ resistance, supports tumorsphere formation, and is associated with a poor prognosis." (PMID 40298811, 2025). "Cell experiments showed that thiamine significantly decreased the malondialdehyde level and increased the levels of superoxide dismutase and catalase in C6 rat glioma cells, inhibiting oxidative stress to some extent." (PMID 36937346, 2023). "In glioma cells, CAT overexpression significantly reduces basal H2O2 level and thus promotes cell growth, inducing resistance against conventional chemo- and radiotherapy." (PMID 36307808, 2022). "It has been reported that intracellular ROS and extracellular H2O2 are increased and sensitivity to radiation, and H2O2 is increased in CAT knockdown glioma cells." (PMID 36035213, 2022). "In a recent report, according to the Cancer Genome Atlas database, glioma tumor tissue represents high CAT mRNA expression compared with normal tissue." (PMID 36307808, 2022). "CAT expression has been correlated with glioma resistance to the chemotherapeutic agent carmustine, a DNA alkylating agent." (PMID 36035213, 2022). "We compared CAT mRNA levels in glioma tumor tissue to levels in control brain tissues in datasets from Rembrandt cohorts comprising results from 537 samples." (PMID 34943091, 2021). "To investigate if CAT expression is clinically relevant in gliomas, we interrogated The Cancer Genome Atlas (TCGA) data accessed via GlioVis." (PMID 34943091, 2021). "In U251 glioma cells, CAT overexpression substantially decreased the basal level of hydrogen peroxide, enhanced anchorage-independent cell growth, and facilitated resistance to the chemotherapeutic drug temozolomide and ionizing radiation." (PMID 34943091, 2021). "We found that human glioma cells stably overexpressing CAT express lower levels of intracellular H2O2 than control cells and are resistant to TMZ and radiation." (PMID 34943091, 2021). "In this study, we further assessed the role of CAT upregulation in glioma cell resistance to therapy and demonstrated that chemo- and radioresistance relies upon the regulation of hydrogen peroxide due, at least in part, to altered expression of CAT." (PMID 34943091, 2021).
glioma (continued). "Given the important role of ROS production in mediating glioma cell sensitivity to radiation, we next examined the effect of radiation on clonogenic survival in the context of CAT overexpression." (PMID 34943091, 2021). "Lastly, the neurobasal media also contains the antioxidants vitamin E, glutathione, pyruvate, catalase, and superoxide dismutase, which help improve glioma cell survival." (PMID 32102678, 2020). "For instance, overexpression of SOD, catalase, GPx, and GR in radioresistant clone of U251 glioma cell line leads to their resistance to cisplatin and radiotherapy." (PMID 26124081, 2015). "In conclusion, we examined the biological rationale for the use of PPAR agonists in glioblastoma, in particular brain tumor growth inhibition, glioma cell differentiation, inhibition of apoptosis, and increased catalase activity." (PMID 24672773, 2014). "We examined 16 single nucleotide polymorphisms (SNPs) of 9 antioxidant genes (GPX1, CAT, PON1, NQO1, SOD2/MnSOD, SOD3, and NOS1*2*3) in 384 glioma and 384 control cases in a Chinese hospital-based case–control study." (PMID 23259684, 2012). "Distinct glioma subtypes, grades, or stages may exhibit unique expression patterns, with earlier studies reporting reduced CAT activity likely examining different tumor populations than those characterized by overexpression in aggressive phenotypes." (PMID 41009025, 2025). "However, functional studies reveal that when CAT is overexpressed in glioma cells, it leads to a more aggressive cancer phenotype." (PMID 41009025, 2025). "Research indicates that under conditions of elevated ROS levels, glioma cells invoke antioxidant defense mechanisms including manganese superoxide dismutase (MnSOD), catalase, and glutathione peroxidase (GPx) to combat oxidative stress and ensure cell survival." (PMID 40452834, 2025). "Besides, due to the high expression of SOD and catalase enzymes in glioma; there is an accelerated conversion of superoxide to hydrogen peroxide in tumour cells which makes astrocytes particularly sensitive to damage induced by ROS." (PMID 35961680, 2023). "In gliomas, catalase appears to be constitutively overexpressed compared with astrocytes." (PMID 36035213, 2022). "We previously reported that CAT activity is elevated in TMZ-resistant glioma cells." (PMID 34943091, 2021). "Importantly, pharmacological inhibition of CAT activity reduced the proliferation of glioma cells isolated from patient biopsy samples." (PMID 34943091, 2021). "In our previous studies, we demonstrated that glioma cell resistance to TMZ-induced oxidative stress is mediated by a reduction in the levels of mitochondrial ROS and enhanced antioxidant production and is associated with increased CAT activity." (PMID 34943091, 2021). "Here, we assessed whether antioxidant catalase (CAT) affects glioma cell sensitivity to temozolomide and radiation." (PMID 34943091, 2021). "Analysis of CAT mRNA in glioma samples of different grades showed that the level of CAT mRNA expression in the tumor correlated inversely with overall survival (OS) in patients (high median CAT expression: OS = 18.0 months; low median CAT expression: OS = 23.4 months; p = 0.0107 by log-rank test)." (PMID 34943091, 2021). "Pretreatment of CAT-overexpressing cells with 3-AT reduced the clonogenic survival after treatment with radiation (p < 0.0001), further suggesting that CAT may protect glioma cells against radiation-induced toxicity." (PMID 34943091, 2021). "Finally, CAT overexpression significantly decreased survival in an orthotopic mouse model of glioma." (PMID 34943091, 2021). "Using The Cancer Genome Atlas database, we found that CAT mRNA expression is upregulated in glioma tumor tissue compared with non-tumor tissue, and the level of expression negatively correlates with the overall survival of patients with high-grade glioma." (PMID 34943091, 2021).